MYC (MYC proto-oncogene, bHLH transcription factor)
Diseases named in the same sentence as MYC in open-access papers (continued):
Sharing a sentence is not in itself a finding about the gene and the disease.
cancer (continued). "The Gene Set Enrichment Analysis (GSEA) analysis showed that PSAT1 can be enriched into the classic signaling pathways of cancer such as mTORC1 signaling, MYC targets and JAK STAT3." (PMID 36105075, 2022). "Emerging evidence indicates that AMBRA1 can also inhibit cancer formation, maintenance, and progression by regulating c-MYC and cyclins, which are frequently deregulated in human cancer cells." (PMID 36237336, 2022). "AXIN2 expression is driven by MYC and overexpressed in multiple human cancers critical to maintain cancer cell aggressiveness via regulation of the beta catenin/wnt pathway." (PMID 36130950, 2022). "Due to the important role of MYC in tumorigenesis, MYC targeting is a useful strategy in the treatment of cancer." (PMID 35370699, 2022). "With the aim to analyze the dynamics occurring between the GFP+ and the GFP− cells during cancer expansion, samples underwent immunofluorescence (IF) assays for MYC and Cas3." (PMID 36704198, 2022). "In response to stromal cues, cancer cells underwent important epigenetic changes (i.e., increased histone acetylation), leading to MYC activation." (PMID 36612058, 2022). "SP1 and MYC are well-known cancer regulators, which have been reported to be highly expressed in diseased tissues." (PMID 36212136, 2022). "As the targeting oncogenic MYC in cancer remains challenging, alternative approaches are under investigation, for instance with the BET-inhibitor OTX015." (PMID 35565249, 2022). "Many human cancers rely on aberrant expression of MYC transcription factor family members to allow unhindered growth and proliferation; high expression levels are predictive of poor clinical outcome." (PMID 35484422, 2022). "As such, we describe our findings that the MYC substitution S146L promotes MYC:TRRAP binding and represents a context-dependent gain-of-function mutation in cancer development." (PMID 36018850, 2022). "The addition of some conventional anti-cancer agents to cell lines with prominent MYC-programs results in reduced cell growth." (PMID 35013227, 2022). "Focal amplification peaks, including the well‐studied cancer‐driven gene MYC (8q.24.21) and several antiapoptotic genes (MCL1, HORMAD1, and ECM1 on 1q21.2), were identified in the high‐risk patients, along with a focal deletion peak at 13q14.2." (PMID 34894177, 2022). "An important role of the kinase has been described in cancer cells with oncogene MYC overexpression, related to protection from oxidative stress resulting from MYC activity." (PMID 36295658, 2022). "The hallmark gene sets of MYC targets V2 (derived from the Molecular Signatures Database) included 58 genes which were regulated by MYC in many cancers." (PMID 36408158, 2022). "MYC, however, is a high-value therapeutic target due to its high prevalence in cancers overexpressing the deregulated protein and the search for possible therapies against this proto-oncogene has persisted." (PMID 36613820, 2022). "The link between PYCR, proline metabolism and the oncogenic transcription factor c-MYC has been studied in other cancers." (PMID 35105345, 2022). "The MYC protein was reported to be a unique carcinogenic driving factor in an article on pan-cancer studies, where c-MYC mainly regulated multiple biological processes by selectively activating gene expression." (PMID 35847930, 2022). "Oncogenic MYC is known to orchestrate a profound rewiring of the metabolic processes in cancer cells." (PMID 35943801, 2022). "To answer these evolutionary questions, we developed an in vivo assay in Drosophila that allowed modulation of MYC levels in single cancer cells within a malignant mass growing in the animal." (PMID 36704198, 2022).
cancer (continued). "MUC1-C activates MYC expression by a WNT pathway-mediated mechanism that is dependent on cancer cell context." (PMID 35612556, 2022). "Although the critical function of MYC in human cancer makes it an ideal target for therapeutic interventions, long‐term inhibition of MYC has been considered infeasible." (PMID 35593206, 2022). "RT-qPCR and Western blot tested the downregulated miR-34a-5p and PTEN, and upregulated c-MYC and DNMT3a in cancer tissues and cells." (PMID 34623601, 2022). "MYC protein is strongly involved in the metabolic shift of cancer cells; thus, glycolysis and glutaminolysis inhibitors have also proven to be effective in tackling cancer cells via a conditional synthetic lethality approach." (PMID 35408915, 2022). "The enhancers physically interact with the MYC gene, which has a longstanding history in cancer biology." (PMID 35990505, 2022). "Further studies are needed to generate a more comprehensive view of how nucleolar resident proteins and ribosomal factors control the activity of MYC and of other growth-promoting factors in normal and cancer cells." (PMID 35159381, 2022). "These inhibitors target the genomic landscape in TNBC by specifically suppressing MYC-driven transcription, inducing further DNA damage, improving anti-cancer immunity, and preventing drug resistance against MAPK and PI3K-targeted therapies." (PMID 36139513, 2022). "The second system that we employed is the Myc-CaP mouse cancer cell line derived from mouse prostate tumours driven by MYC under the control of an androgen-responsive element." (PMID 35945217, 2022). "USP22 is a functional mediator necessary for MYC to promote cancer and can increase the stability and tumorigenic activity of MYC in cancer cells." (PMID 35935969, 2022). "Our results have, moreover, identified several key steps that represent plausible therapeutic targets to downregulate MYC expression in cancer." (PMID 35017527, 2022). "MYC-driven cancer cells were found to be highly dependent on IRE1α/XBP1 and exquisitely sensitive to pharmacological inhibition of IRE1α." (PMID 35349489, 2022). "The oncogenic transcription factor MYC drives the rewiring of multiple metabolic pathways in a broad spectrum of cancers, enhancing glycolysis, glutaminolysis, oxidative phosphorylation (OXPHOS), and nucleotide and amino acid synthesis." (PMID 35740646, 2022). "In mouse models of TNBC proficient or deficient of breast cancer type 1 susceptibility gene (BRCA1), MYC overexpression dramatically decreases lymphocyte infiltration in tumors, along with immune signature remodelling." (PMID 36323660, 2022). "Aberrant expression of MYC transcription factor family members predicts poor clinical outcome in many human cancers." (PMID 35484422, 2022). "The identification of OTUB1 as a stabilizer of c-MYC reveals a new potential target for treating c-MYC in cancers." (PMID 35159073, 2022). "Given the role of MYC levels on cancer outcome, it is assumed that its amount and activity are under tight control and regulation during normal cell life." (PMID 36430960, 2022). "Altogether, we are witnessing the emergence of diverse rationally designed strategies, which shall significantly expand our toolbox to tackle oncogenic MYC and improve cancer patient outcomes." (PMID 36214609, 2022). "In total, the cell lines span lymphocyte, epithelial, and mesenchymal cancer subtypes providing a broad cellular view of MYC overexpression." (PMID 35594991, 2022). "This review summarizes the clinical evidence and molecular mechanisms linking MYC and therapy resistance, and discusses possible innovative strategies to target the specific vulnerabilities of MYC‐driven cancer." (PMID 36214609, 2022). "Instead, evaluating the expression of over 350 MYC target genes to determine MYC transcriptional activity has been shown to more accurately predict cancer patient outcomes." (PMID 35741402, 2022).
cancer (continued). "The effects of promising PSMs on c-MYC expression were assessed using luciferase reporter assay and qPR-PCR in cancer and immortalized cultured cells." (PMID 36012470, 2022). "FAM83H translocates to the nucleus in cancer cells where it acts in conjunction with MYC and the Wnt/β-catenin pathway to stimulate cell proliferation and induce EMT." (PMID 36232920, 2022). "BET inhibitors are becoming resistant in cancer therapy due to increased Wnt signaling catenin-mediated MYC in AML and activation of the RAS pathway in lymphoma." (PMID 36286044, 2022). "Given the observation of higher expression of MYC pathways in type II tumors, and the known role of MYC in cancer cell metabolism, we used DESI-MS imaging to assess the in situ metabolomic profiles of tissue sections from 25 type I and 20 type II tumors." (PMID 36239936, 2022). "MYC is one of the most common contributors to tumorigenesis, and its expression is estimated to be elevated or dysregulated in up to 70% of human cancers." (PMID 35090497, 2022). "In cancer cells, miR-22 targets the myelocytomatosis oncogene (MYC) gene to regulate fatty acid metabolism, and MYC is highly expressed during muscle development." (PMID 36077994, 2022). "Recently, we showed that TNKS1/2 inhibition cell-type dependently can block WNT/β-catenin and/or YAP signaling, and consequently MYC proto-oncogene bHLH transcription factor (MYC) signaling, resulting in attenuated cancer cell growth." (PMID 36873622, 2022). "Considering the link of MYC to inflammation and cancer, it would be interesting to further explore its role in the context of aging and promoter‐proximal Pol II pausing." (PMID 36082605, 2022). "Together, these data suggest that targeting c-MYC can be exploited as a clinically meaningful therapeutic strategy, making c-MYC one of the most enticing targets for cancer drug development." (PMID 35267559, 2022). "Since the ATR‐CHK1 branch of the DNA damage response mitigates genome instability in cancer cells, inhibiting this signaling axis has the potential for a MYC‐SL." (PMID 36214609, 2022). "The oncogene c-MYC is a key driver of cancer cell growth, and it helps boost transcription- and translation-related processes; thus, c-MYC is thought to drive RiBi." (PMID 35565259, 2022). "Both c-MYC signaling and polyamine synthesis are frequently activated in human cancers, especially during the early-stage development of CRC." (PMID 36457036, 2022). "Recently, accumulating studies show that MYC-overexpressing cancers are sensitive to small-molecule BRD inhibitors, such as JQ159–61." (PMID 35504924, 2022). "Overall, MYC is believed to be dysregulated in approximately 70% of cancers Deregulation is mediated by multiple different mechanisms including gene amplification, gene translocation, altered methylation and enhanced intracellular signaling." (PMID 35908121, 2022). "It not only interacts with MYC to promote cancer progression but also performs different oncogenic functions independent of MYC." (PMID 35965522, 2022). "For instance, a CBS located 2 kb upstream of the MYC promoter is conserved in multiple cancer cell lines." (PMID 35993175, 2022). "Cancer cells often experience high basal levels of DNA replication stress (RS), for example due to hyperactivation of oncoproteins like MYC or RAS." (PMID 35393546, 2022). "Prior work found that in 98% of cancers with MYC copy number increases, the amplified region includes the PVT1 gene." (PMID 36139061, 2022). "MYC (c-Myc) is a proto-oncogene involved in multiple cancers that impacts many biological events, including cell proliferation, differentiation, and programmed cell death, when aberrantly regulated." (PMID 36452487, 2022). "The G4 motif of the c-MYC promoter was chosen for our subsequent study as this gene product is the major oncogenic driver in cancer." (PMID 36012470, 2022).
cancer (continued). "Our analysis indicates that OTUB1 acts as an oncogene in this c-MYC-dependent cancer type and that overexpression of OTUB1 increases c-MYC protein levels." (PMID 35159073, 2022). "The m6A regulators regulated the m6A methylation in MYC, affecting the stability and translation efficiency of MYC, and then regulated the expression of MYC, which was an important mechanism for the occurrence and development of cancers." (PMID 36120320, 2022). "It appears evident that targeting MYC in cancer cells would reverse all oncogene-induced effects, restore physiological cell state, or induce apoptosis." (PMID 36611833, 2022). "The remaining pathways MYC targets, angiogenesis, Wnt/β-catenin signaling and KRAS signaling are associated with cancer." (PMID 36009267, 2022). "MYC alterations have been found in cancer but were mutually exclusive with PIK3CA, PTEN, APC, or BRAF alterations, suggesting that MYC is a distinct oncogenic driver." (PMID 35328644, 2022). "The MYC oncogene is deregulated in multiple cancers, and its overexpression increases cyclins (A and E) and CDK expression." (PMID 35740522, 2022). "MYC interacts directly or indirectly with a broad repertoire of epigenetic modifiers and thereby influences the epigenome of cancer cells." (PMID 35439169, 2022). "BNIP3-positive cancer cells have an upregulated activity in reactive oxygen species pathway, oxidative phosphorylation, as well as MYC targets." (PMID 35912211, 2022). "SEC inhibitors, which presents a novel class of TMi’s, specifically inhibit MYC-target genes which is most effective in MYC-driven cancers." (PMID 36139513, 2022). "Aberrant c-Myc expression is frequently found in inflammation and cancer and MYC is thus considered a promising therapeutic target but it is also an “undruggable” target." (PMID 36187481, 2022). "CCAT2 was reported to induce chromosomal instability and metastases and modulate MYC expression, known to regulate kinds of axis controlling molecular process and cancer metabolism." (PMID 35170195, 2022). "Oncogenesis driven by the signaling of HGF-induced MET/PI3K/AKT/c-MYC has been well-characterized in many different cancer types." (PMID 35941699, 2022). "This highlights MACC1 as a potential CCG, expanding the repertoire of CCGs involved in several hallmarks of cancer, including the cell cycle, proliferation and invasion, similar to MYC and RAS." (PMID 35884519, 2022). "Overall, our findings highlight that the dual inhibition of PI3K and HDAC by CUDC-907 is an effective therapeutic strategy for NB and other MYC-dependent cancers." (PMID 35205815, 2022). "Considering the role played by MYC in cancer metabolism, FDG-PET was performed after one cycle to evaluate metabolic responses." (PMID 35681657, 2022). "The MYC transcription factor is a significant driver of cancer growth and is known to regulate glucose uptake, lipid synthesis and polyamine synthesis." (PMID 35903898, 2022). "The top 22 significantly cancer-associated terms of the GSEA were identified, including oxidative phosphorylation, MYC target, the mTORC1 signaling, E2F target, metabolism-associated pathway, DNA repair, PI3K/AKT/mTOR signaling." (PMID 36209249, 2022). "For example, cancer cells were sensitive to oxaliplatin with the elevated expression of MYC, whereas they were insensitive with the increased expression of ACSS2." (PMID 36119478, 2022). "For instance, CDK7 inhibitors commonly repress MYC, an oncogene overexpressed in 70% of human cancers." (PMID 35757006, 2022). "JQ1′s effect on MYC has been confirmed in many other cancer types, including AML and Burkitt’s lymphoma." (PMID 35053311, 2022). "Cancer cells with deregulated MYC are specifically characterized by a mitotic vulnerability, and AURKB was demonstrated to be synthetically lethal with MYC." (PMID 35439169, 2022). "We then used another MYC targeting agent, Omomyc, a peptide reported to act as a dominant negative agent blocking MYC function in cancer cells." (PMID 36433941, 2022).
cancer (continued). "Dysregulated IGF2BP2 expression leads to the accumulation of oncogenic molecules, such as MYC, thus supporting the malignant state of cancer cells." (PMID 35002506, 2022). "Well-characterized target genes have been described, including those belonging to the HES and HEY gene family, CCND1 and MYC, influencing cancer cell proliferation." (PMID 35682974, 2022). "Mechanisms that contribute to MYC deregulation in cancers include retroviral insertions, chromosomal translocations, locus amplification, and hyper-activation of oncogenic signal transduction pathways." (PMID 36139061, 2022). "Genetic alterations affecting MYC proto-oncogenes and MYC-related signaling pathways are among the most common in human cancers." (PMID 36012403, 2022). "The c-MYC oncogene is one of the best studied cancer driver genes, promoting tumorigenesis via diverse mechanisms such as stimulating cell proliferation, blocking apoptosis, altering metabolism and depressing host immunity." (PMID 35908121, 2022). "c-MYC increases cancer cell proliferation by upregulating glutaminase, an enzyme involved in the conversion of glutamine to glutamate." (PMID 35105345, 2022). "Nevertheless, significant effort has been devoted to understanding the mechanisms of oncogenic MYC activity with the objective of uncovering novel vulnerabilities of MYC-dependent cancers." (PMID 36018850, 2022). "Alterations of the MYC gene, such as translocation and amplification, are well established events that lead to MYC activation and formation of cancer." (PMID 36018850, 2022). "Upregulation of POLR3G, which is driven by MYC, identifies a subgroup of patients with unfavorable survival outcomes in specific cancers, further implicating the POLR3G-enhanced transcription repertoire as a potential disease factor." (PMID 35637192, 2022). "Here, we selectively focus on the available clinical data linking oncogenic MYC to therapy resistance in diverse cancer types." (PMID 36214609, 2022). "Lastly, we tested the regulatory impact of the differential expression of the well-known cancer-related TF MYC on the expression of its target genes." (PMID 35575458, 2022). "As a result, MYC S146L more potently drives the acquisition of cancer hallmarks than WT, while also promoting the pleiotropic effects of MYC in both cell proliferation and apoptosis." (PMID 36018850, 2022). "Instead, we found significant enrichment (p < 0.05) of three hallmarks of cancer: unfolded protein response, DNA damage repair, and MYC targets." (PMID 36139061, 2022). "In particular, PPRHs interfering with promoter activation (HpMYC-G4-PR-C) and transcription (HpMYC-I1-T) dose- and time-dependently regulated these cancer cells and decreased MYC and downstream Cyclin D1 expression at concentrations as low as 25 nM." (PMID 36613820, 2022). "The concept of targeting MYC to confer responsiveness to MET inhibition is supported by previous studies showing that MYC blockage overcomes the resistance of other types of cancer cell lines to MET inhibitors." (PMID 36433941, 2022). "Among these, MYC was of our interest, because MYC is proved to be a critical oncogene that drives many types of cancer tumorigenesis." (PMID 35264565, 2022). "In summary, thymoquinone and quercetin have been shown to be more suitable for suppressing c-MYC expression in cancer cells as they inhibited c-MYC promoter activity in both Luciferase reporter assay and qRT-PCR analysis." (PMID 36012470, 2022). "At the molecular pathway level, a high W-E signature promoted cell proliferation across cancer types via high expression of the G2/M checkpoint and E2F/MYC target genes." (PMID 35794212, 2022). "An increasing number of studies have reported that some genes promote cancer progression by activating the MYC pathway." (PMID 36482116, 2022).